USP7 (ubiquitin specific peptidase 7)
Description:
In association with DAXX, is involved in the deubiquitination and translocation of PTEN from the nucleus to the cytoplasm, both processes that are counteracted by PML. Deubiquitinates KMT2E/MLL5 preventing KMT2E/MLL5 proteasomal-mediated degradation. Involved in cell proliferation during early embryonic development. Involved in transcription-coupled nucleotide excision repair (TC-NER) in response to UV damage: recruited to DNA damage sites following interaction with KIAA1530/UVSSA and promotes deubiquitination of ERCC6, preventing UV-induced degradation of ERCC6. Involved in maintenance of DNA methylation via its interaction with UHRF1 and DNMT1: acts by mediating deubiquitination of UHRF1 and DNMT1, preventing their degradation and promoting DNA methylation by DNMT1. Deubiquitinates alkylation repair enzyme ALKBH3. OTUD4 recruits USP7 and USP9X to stabilize ALKBH3, thereby promoting the repair of alkylated DNA lesions. Acts as a chromatin regulator via its association with the Polycomb group (PcG) multiprotein PRC1-like complex; may act by deubiquitinating components of the PRC1-like complex. Able to mediate deubiquitination of histone H2B; it is however unsure whether this activity takes place in vivo. Exhibits a preference towards 'Lys-48'-linked ubiquitin chains. Increases regulatory T-cells (Treg) suppressive capacity by deubiquitinating and stabilizing the transcription factor FOXP3 which is crucial for Treg cell function. Plays a role in the maintenance of the circadian clock periodicity via deubiquitination and stabilization of the CRY1 and CRY2 proteins. Deubiquitinates REST, thereby stabilizing REST and promoting the maintenance of neural progenitor cells. Deubiquitinates SIRT7, inhibiting SIRT7 histone deacetylase activity and regulating gluconeogenesis. Involved in the regulation of WASH-dependent actin polymerization at the surface of endosomes and the regulation of endosomal protein recycling. It maintains optimal WASH complex activity and precise F-actin levels via deubiquitination of TRIM27 and WASHC1. Mediates the deubiquitination of phosphorylated DEPTOR, promoting its stability and leading to decreased mTORC1 signaling. Deubiquitinates H2AB1, H2BC4 and H2BC22 (By similarity). (Microbial infection) Contributes to the overall stabilization and trans-activation capability of the herpesvirus 1 trans-acting transcriptional protein ICP0/VMW110 during HSV-1 infection. (Microbial infection) Upon infection with Epstein-Barr virus, the interaction with viral EBNA1 increases the association of USP7 with PML proteins, which is required for the polyubiquitylation and degradation of PML.
Synonyms: HAUSP; C16DELp13.2; DEL16P13.2; HAFOUS; TEF1
Tractability: Small molecule: a structure with a bound ligand is known; a high-quality ligand is known; it has a binding pocket of medium quality; it belongs to a druggable protein family. PROTAC: UniProt records ubiquitination sites on it; ubiquitination databases record sites on it; its protein half-life has been measured; a small molecule that binds it is known.
Target class: Cysteine protease; Cysteine protease CA clan; Protease; Enzyme; Cysteine protease C19 family
Chemical probes: FT671 (high quality)
Gene: Protein-coding gene on chromosome 16 (8,892,097 to 8,975,328, reverse strand). Ensembl gene ENSG00000187555.
Subcellular location: Nucleus; Cytoplasm; Nucleus, PML body; Chromosome
Subcellular location (Human Protein Atlas): Nucleoplasm; Cytosol; Nuclear bodies
Pathways (Reactome):
DNA Repair: Dual incision in TC-NER; Formation of TC-NER Pre-Incision Complex; Gap-filling DNA repair synthesis and ligation in TC-NER; Transcription-Coupled Nucleotide Excision Repair (TC-NER)
Metabolism of proteins: Synthesis of active ubiquitin: roles of E1 and E2 enzymes; Ub-specific processing proteases
Signal Transduction: Regulation of PTEN localization
Gene Ontology:
Molecular function: cysteine-type deubiquitinase activity; cysteine-type endopeptidase activity; deubiquitinase activity; K48-linked deubiquitinase activity; protein binding; histone H2A deubiquitinase activity; histone H2B deubiquitinase activity
Biological process: antiviral innate immune response; DNA alkylation repair; monoubiquitinated protein deubiquitination; negative regulation of gene expression via chromosomal CpG island methylation; negative regulation of gluconeogenesis; negative regulation of proteasomal ubiquitin-dependent protein catabolic process; negative regulation of TORC1 signaling; protein deubiquitination; protein stabilization; regulation of circadian rhythm; regulation of establishment of protein localization to telomere; regulation of protein stability; regulation of retrograde transport, endosome to Golgi; regulation of tumor necrosis factor-mediated signaling pathway; symbiont-mediated disruption of host cell PML body; transcription-coupled nucleotide-excision repair; protein K48-linked deubiquitination; protein K63-linked deubiquitination; protein ubiquitination; regulation of telomere capping
Cellular component: chromosome; cytoplasm; cytosol; nuclear body; nucleoplasm; nucleus; peptidase complex; PML body; protein-containing complex; ubiquitin ligase complex
Genetic constraint (gnomAD): Loss-of-function variants: 7 observed, 153.98 expected, observed/expected ratio (o/e) 0.0455, 90% interval 0.025 to 0.085. The upper end of that interval is the gene's LOEUF score, 0.085, which puts it in group 1 of 6, group 1 being the genes least tolerant of losing a copy. Missense variants: 690 observed, 1,391.9 expected, observed/expected ratio (o/e) 0.5, 90% interval 0.47 to 0.53. Synonymous variants: 547 observed, 488.11 expected, observed/expected ratio (o/e) 1.12, 90% interval 1.04 to 1.2.
Gene-disease validity (ClinGen):
ClinGen rates the evidence that USP7 causes each of these diseases.
Hao-Fountain syndrome (autosomal dominant): Definitive.
Homologues: Orthologues: macaque USP7 (99% identical), dog USP7 (99% identical), guinea pig USP7 (99% identical), mouse Usp7 (99% identical), chimpanzee USP7 (98% identical), pig USP7 (98% identical), rat Usp7 (97% identical), tropical clawed frog usp7 (96% identical), rabbit USP7 (95% identical), zebrafish usp7 (94% identical), Drosophila melanogaster Usp7 (50% identical). Paralogues in human: USP48 (19% identical), USP9X (14% identical), USP9Y (13% identical), USP24 (13% identical), USP34 (12% identical), USP40 (12% identical), USP47 (12% identical), USP42 (11% identical), USP31 (11% identical), USP36 (11% identical), USP28 (10% identical), USP32 (10% identical), and 59 more.
Diseases named in the same sentence as USP7 in open-access papers:
USP7 is named in the same sentence as 201 diseases in open-access papers, as found by Europe PMC text mining. Sharing a sentence is not in itself a finding about the gene and the disease. The quoted sentences say what the papers report.
breast carcinoma (64 papers, 2014 to 2026). "In line with our data, the DUB Usp7, also known as Herpesvirus associated protease (HAUSP), is generally known to act tumor-promoting in various cancers 67-69,80, including breast cancer 70-73." (PMID 35673573, 2022). "At the same time, PHF8 contributes to the abundance of USP7 in breast cancer by transcriptionally facilitating its encoding genes." (PMID 34575114, 2021). "This accumulation is in positive correlation with the literature showing that USP7 inhibition causes a G0–G1 arrest in breast cancer cell lines (Xia at al., 2019)." (PMID 32922122, 2020). "For breast cancer, studies indicate an association between USP7 dysregulation and worse prognosis." (PMID 38672118, 2024). "USP7 inactivation caused alterations in cell cycle regulation of breast cancer cell lines." (PMID 32922122, 2020). "Interestingly, a recent report also demonstrated a link between USP7, a ubiquitin hydrolase regulating Geminin stability, and breast cancer-specific survival, suggesting that USP7 might be implicated in Geminin deregulation during breast cancer progression." (PMID 30241373, 2018). "For instance, in breast cancer, exosomal circ-0100519 was reported to induce M2 macrophage polarization via the USP7/NRF2 axis, thereby skewing the immune microenvironment toward a suppressive state." (PMID 41438756, 2025). "Recent work has identified USP7 as a deubiquitinase for ZMYND8 that promotes breast cancer cell migration and invasion, underscoring the importance of DUBs in modulating ZMYND8-driven oncogenic programs." (PMID 41297414, 2025). "In vitro and in vivo studies suggest that USP7 deubiquitination leads to LSD1 overexpression in numerous cancer types (including breast cancer), consequently promoting cancer metastasis." (PMID 41157055, 2025). "This study reveals the EMC2/USP7/ENO1/B-MYB protumorigenic axis in breast cancer and identifies EMC2 as a candidate target for PDK1/AKT inhibitory therapy." (PMID 40303285, 2025). "The downregulation of USP7 expression significantly inhibits the proliferation and growth of breast cancer cells." (PMID 40936898, 2025). "Exosomal circ-0100519 promotes M2 macrophage polarization via the USP7/NRF2 pathway in breast cancer, activating downstream antioxidant and metabolic genes that reinforce an immunosuppressive macrophage phenotype." (PMID 41438756, 2025). "This study aims to investigate how a deregulated USP7 expression affects chromosomal instability and prognosis of breast cancer patients in silico and radiosensitivity and DNA repair in breast cancer cells in vitro." (PMID 38672118, 2024). "For instance, in breast cancer cells, the dysregulation of USP7 disrupts S-phase-specific DNA repair and exacerbates DNA replication stress, potentially resulting in increased chromosomal instability and reduced overall survival rate." (PMID 39767641, 2024). "The significantly decreased OS of breast cancer patients with high USP7 expression is also consistent with observations from another study." (PMID 38672118, 2024). "Next, the impact of USP7 mRNA expression on the overall survival (OS) of breast cancer patients was analyzed." (PMID 38672118, 2024). "The study results indicated an association between altered USP7 expression and CIN, which is associated with poor prognosis in many tumors, including breast cancer." (PMID 38672118, 2024). "The circ‐0100519/USP7/NRF2 axis promotes the progression of breast cancer through regulating M2 macrophage polarisation." (PMID 39107958, 2024). "For breast cancer, there is some evidence that both low and high USP7 expression correlates with poor breast cancer specific survival in luminal and triple-negative breast cancer." (PMID 38672118, 2024).
breast carcinoma (continued). "In parallel, the effects of a deregulated USP7 expression in breast cancer tumors in silico and for the first time, its effects on radiosensitivity in breast cancer cell lines of different subtypes in vitro were analyzed." (PMID 38672118, 2024). "It showed that USP7 mRNA expression is very heterogeneous across all breast cancer subtypes with comparable amounts of normal-, low- and high-expressing tumors." (PMID 38672118, 2024). "The investigations in silico were performed using overall survival and USP7 mRNA expression data of breast cancer patients." (PMID 38672118, 2024). "Since geminin is a USP7 substrate, our results imply that USP7 overexpression contributes to breast cancer development by stabilizing geminin." (PMID 37605223, 2023). "For instance, in a collection of aggressive breast cancers, the levels of the proteins USP7 and geminin were significantly correlated." (PMID 37605223, 2023). "Previous studies have shown that USP7 is able to act synergistically with PI3K inhibitors to inhibit breast cancer development." (PMID 36311703, 2022). "USP7 overexpression correlates with various malignancies, including epithelial cancer, prostate cancer, breast cancer, lung cancer, and cervical cancer, through the regulation of cancer-promoting or tumor-suppressing proteins." (PMID 35163710, 2022). "Our data confirmed the known tumor promoting function of Usp7 and Metap2 in murine and human breast cancer cells, postulating a new importance of Metap1 for breast cancer cell growth." (PMID 35673573, 2022). "Further, a slightly but significantly reduced PI3K pathway activity was observed upon USP7 knockdown in human breast cancer cells and impaired cell cycle progression was observed in murine and human Usp7 knockdown breast cancer cells." (PMID 35673573, 2022). "In line with the known tumor promoting function of these proteases we demonstrated Usp7 and Metap2 to be important for murine and human breast cancer cell growth and discovered a role for Metap1 in this context." (PMID 35673573, 2022). "Although there has been no investigation into the effect of chemical USP7 inhibitors in melanoma cells, the USP7 inhibitors FT827 and FT671 showed high potency for suppressing USP7 activity in breast cancer cells." (PMID 35163049, 2022). "Our results show that activated cGAS can be colocalized with the deubiquitinase USP7 in breast cancer cells, and USP7 can stabilize activated cGAS in the cGAS–STING pathway by affecting the ubiquitination of cGAS." (PMID 35163710, 2022). "For example, Usp7 is known to act as tumor-promoting in various cancer entities including breast cancer." (PMID 36313646, 2022). "To study a possible connection of Usp7 to PI3K signaling, we examined the activity of the PI3K pathway by phosphorylation status of three players (Akt, mTOR, S6) upon USP7 knockdown in human breast cancer cells." (PMID 35673573, 2022). "In breast cancer, a functional link between USP7 and PHF8 was seen through their interaction and a positive feedback mechanism." (PMID 34577547, 2021). "Reports have shown that USP7 overexpression is an indicator of poor prognosis for breast cancer patients." (PMID 34575114, 2021). "PHF8 is stabilized by USP7 through deubiquitination, resulting in increased expression of cyclin A2, which promotes the proliferation of breast cancer cells and accelerates tumor growth." (PMID 34575114, 2021).
breast carcinoma (continued). "In conclusion, interfering USP7 deubiquitinase activity elevates breast cancer sensitivity to radiation therapy." (PMID 34575114, 2021). "Stable knockdown of OTUD7B or USP7 markedly inhibited breast cancer cell proliferation and migration, reduced tumor growth and metastasis in vivo." (PMID 34035221, 2021). "ECT2, which is deubiquitinated and stabilized by USP7, was found to enhance breast cancer cell proliferation in vitro and cancer growth in vivo by positively regulating the classical oncogenic signaling axis mediated by MDM2." (PMID 34575114, 2021). "ERα is deubiquitinated and stabilized by USP7, which in turn promotes cell proliferation and tumor growth in ERα+ breast cancer through inhibiting cell cycle arrest and apoptosis." (PMID 34575114, 2021). "In MCF7 breast cancer cells it was observed that USP7 deubiquitinates and stabilizes PHF8 during DNA damage response, contributing to the activation of DNA repair mechanisms." (PMID 34577547, 2021). "CFU assay was performed to identify the alterations in colony-forming ability of the breast cancer cells after allosteric inhibition of USP7." (PMID 32922122, 2020). "Previous studies have demonstrated that p5091, which is a specific inhibitor of USP7, blocks cell proliferation of different types of cancers such as ovarian, prostate, and breast cancers (Xia at al., 2019)." (PMID 32922122, 2020). "We found that, when staining was scored according to the mean intensity extent of immunopositivity, ECT2 and USP7 together with MDM2 were highly expressed in breast carcinoma samples, and the levels of their expression correlated with each other." (PMID 32929379, 2020). "The current study aims to investigate the promoting role of USP7 in breast cancer cell lines in vitro using small-molecule–based inhibition and siRNA/shRNA-based knockdown strategies to downregulate USP7 in MCF7 and T47D cell lines in vitro." (PMID 32922122, 2020). "Collectively, these results suggested that ECT2/USP7 circuit is potentially linked to breast carcinogenesis, and ECT2 coordinates with USP7 to promote breast cancer cell survival, at least, via activating oncogenic MDM2." (PMID 32929379, 2020). "Here, we found that ECT2 coordinates with USP7 to form a feedforward circuit and promote breast cancer cell survival in a GEF activity-independent manner." (PMID 32929379, 2020). "Next, we found that both ECT2 and USP7 are significantly overexpressed in a subset of breast cancer patients and the levels of these two factors positively correlate with each other." (PMID 32929379, 2020). "USP7 has also been suggested as a potential target for sensitization in breast cancer treatment, where USP7 is frequently upregulated and confers resistance to genotoxic insult, by stabilizing PHF8." (PMID 32850836, 2020). "MTS assay was performed to understand the effect of USP7 inhibitor p5091 on the cell viability of breast cancer cell lines for 3 days." (PMID 32922122, 2020). "Although highly expressed USP7 has been linked to breast carcinogenesis 42, it is less defined what determines the upregulation of USP7 in breast cancer." (PMID 32929379, 2020). "Restriction of USP7 activity strongly enhanced apoptotic gene expression and reduced metastatic ability of breast cancer cell lines." (PMID 32922122, 2020). "Apart from the inhibition of USP7 activity via small-molecule inhibition, siRNA knockdown strategy was used to reduce USP7 at the molecular level to understand the regulatory role of USP7 on breast cancer cell proliferation and growth in vitro." (PMID 32922122, 2020). "In a way, our study provides a rationale for validating USP7/ECT2 as a viable therapeutic target for breast cancer." (PMID 32929379, 2020).